ZEB2 (zinc finger E-box binding homeobox 2)
Diseases named in the same sentence as ZEB2 in open-access papers (continued):
Sharing a sentence is not in itself a finding about the gene and the disease.
melanoma (continued). "Similarly, Zeb2, which is recognized as a mesenchymal marker in the context of epithelial cancers, does not promote invasion in melanoma but rather induces melanocytic differentiation." (PMID 40037534, 2025). "Of note, ZEB1 and ZEB2 TF activity could not be reliably assessed based on DoRothEA pan-cancer database, because of melanoma cell-type specificities." (PMID 38519642, 2024). "Similarly, the inhibition of SNAI2 or ZEB2 expression by siRNA, which led to an increase in ZEB1 expression, resulted in a significant reduction in cell stiffness correlated with an increase in the aspect ratio of melanoma cells and a decrease in circularity." (PMID 38398085, 2024). "While different studies used ZEB2 and ZEB1 as additional markers to define the proliferative (MITFhigh/AXLlow) or invasive (MITFlow/AXLhigh) phenotypes, respectively, our data further demonstrated that EMT-TFs are major regulators of melanoma cell plasticity that fuel intra-tumor heterogeneity." (PMID 32759677, 2020). "We also studied human melanoma datasets from The Cancer Genome Atlas (TCGA), and found that the TET proteins, especially TET2 were downregulated, and the mesenchymal marker Vimentin and EMT master transcription factors like ZEB2, SNAIL2 and TWIST1 were up regulated." (PMID 27852070, 2017). "Thin primary melanomas (such as MM28, Breslow = 0.8 mm) or thick primitive melanomas (such as MM25, Breslow = 16 mm) displayed a proliferative/differentiated ZEB2+ MITF+ SOX10+ phenotype with no or low ZEB1, SOX9 and NGFR expression." (PMID 38519642, 2024). "In the melanoma FTMs, RFs did not affect ZEB1 expression but clearly induced ZEB2 protein expression at the ingrowth areas compared to the PFs." (PMID 36232952, 2022). "Recent data in transgenic mouse models indicated that Zeb2 knock-out is not sufficient to promote melanoma initiation in the mouse and even impairs NRASQ61-dependent melanoma formation, thus precluding a bona fide tumor-suppressor role." (PMID 32759677, 2020). "ZEB2 and SLUG are mostly considered to be pro‐proliferative and pro‐differentiative markers, not involved in the EMT process in melanoma) and revealed a pattern showing only minimal changes." (PMID 29369499, 2018). "However, unlike epithelial cancers, in melanoma ZEB1 and ZEB2 are reported to be differentially expressed in alternate phenotypic states." (PMID 25763355, 2015).
colorectal cancer (64 papers, 2014 to 2025). A primary or metastatic malignant neoplasm that affects the colon or rectum. "Overexpression of ZEB2 is implicated in various malignant carcinomas, reflecting that ZEB2 promotes tumor metastasis, invasiveness and correlates with poor prognosis of human colorectal cancer, glioma, acute myeloid leukemia and small cell lung cancer." (PMID 30979827, 2019). "Glutamine deficiency might reduce E-cadherin in colorectal cancer through increasing zeb1 and zeb2, further studies are needed to confirm this finding." (PMID 35869517, 2022). "This diagnostic study investigates whether nuclear ZEB2 expression in colorectal cancer is associated with early recurrence and reduced survival in 2 independent patient cohorts." (PMID 30646224, 2018). "Specifically, ZEB1 was found to be significantly associated with poor OS for pancreatic cancer, gastric cancer and colorectal cancer patients, while ZEB2 was found to be significantly associated with poor OS for hepatocellular carcinoma and gastric cancer patients." (PMID 28416756, 2017). "DHA has been shown to suppress expression of EMT-related genes including SNAIL, SLUG, ZEB1, and ZEB2 in colorectal cancer cells, resulting in decreased expression of N-cadherin and vimentin, increased E-cadherin expression, and reduced cell migration." (PMID 41009329, 2025). "In colorectal carcinoma, ZEB2 was highly upregulated in a subgroup of quiescent/slow-cycling cells, inducing pCRAF/pASK1 elevation and then chemoresistance." (PMID 40510028, 2025). "In colorectal carcinoma, a clinical study showed that ZEB2 upregulation is related to early recurrence and reduced survival." (PMID 40510028, 2025). "The clinical relevance of ZEB2 as a potential biomarker has been underscored in both, ovarian and colorectal cancers, wherein elevated ZEB2 correlated with poor prognosis, recurrence, and metastasis." (PMID 38719798, 2024). "The expression profiling of these proteins was consistent with the reported literature, which detected over-expression of ZEB1 and ZEB2 in human cancers, including lung cancer, prostate cancer, colorectal cancer, and bladder cancer." (PMID 38751602, 2024). "In colorectal cancer, ZEB2 undergoing glycogen synthase kinase-3 beta (GSK3β) phosphorylation shows migratory potential, while ectopic expression of ubiquitin-specific protease 14 (USP14) is linked to liver and lymph node metastasis." (PMID 37174083, 2023). "A study on colorectal cancer (CC) cells revealed that ectopic expression of ZEB2 was responsible for increasing proliferation and metastatic potential in vivo and in vitro in HCT166 cell lines." (PMID 37174083, 2023). "In colorectal cancer, miR-377-3p suppressed Wnt/ß-catenin signaling by directly targeting ZEB2 and XIAP, thus inhibiting the tumor progression." (PMID 35057851, 2022). "ZEB2 dysregulation is observed in many types of tumors, including gastric cancer, colorectal cancer, pancreatic cancer and LSCC." (PMID 35435130, 2022). "The lncRNA UICLM (upregulated in colorectal cancer liver metastasis) regulates zinc finger E-box binding homeobox 2 (ZEB2) expression by acting as a ceRNA of microRNA-215, thereby promoting liver metastasis of colorectal cancer." (PMID 33558499, 2021). "UICLM promoted colorectal cancer metastasis by acting as a ceRNA which sponges miRNA-215 to regulate ZEB2 expression." (PMID 33658048, 2021). "Here, we show that the expression of ZEB2 marks reduced overall and disease‐free survival in primary and secondary colorectal cancers (CRCs)." (PMID 33931939, 2021). "H19 facilitates the EMT by sponging MiR-138 and MiR-200a to promote ZEB1 and ZEB2 in colorectal cancer." (PMID 33193379, 2020).
colorectal cancer (continued). "For instance, lncRNA UICLM functions as a ceRNA in colorectal cancer and promotes its liver metastasis by regulating miRNA-215/ZEB2 axis." (PMID 32231464, 2020). "As an example, UICLM promotes the metastasis of colorectal cancer by serving as a ceRNA of ZEB2 via interacting with microRNA-215." (PMID 32110804, 2020). "ZEB2 expression was significantly correlated with Sp1 expression in human colorectal cancers (n = 244, r = 0.200, P = 0.00166 and n = 382, r = 0.166, P = 0.00113 for TCGA, Nature 2012, and TCGA, Provisional, studies, respectively)." (PMID 29416649, 2018). "ZEB2 is overexpressed in several cancer types (e.g., breast, ovarian and colorectal cancer) which are correlated with metastasis and poor prognosis." (PMID 30445998, 2018). "For instance, in colorectal cancer, lncRNA UICLM acts as a ceRNA for miR-215 to regulate ZEB2 expression and promote colorectal cancer metastasis." (PMID 30098599, 2018). "Similar mechanism was also reported elsewhere that miR-132 inhibited colorectal cancer cell invasion and metastasis via directly targeting ZEB2." (PMID 28546810, 2017). "In colorectal cancer a graduated, often concentric epithelial differentiation is clearly detectable, and ZEB2 was found overexpressed of at the invasion front, predominantly in the cytoplasm." (PMID 26136338, 2015). "Moreover, the downregulated miR-132-3p predicts the worse prognosis of colorectal cancer, and miR-132-3p suppresses colorectal cancer metastasis via regulating zinc-finger E-box-binding homeobox-2 (ZEB2)." (PMID 33685455, 2021). "H19 may promote EMT by sponging miRNA-138 and miR-200a, and then upregulation of their downstream targets Vimentin,ZEB1 and ZEB2 in colorectal cancer." (PMID 33267897, 2020). "The findings suggest that epithelial to mesenchymal transcription factor ZEB2 is a biomarker with clinical potential and may improve TNM risk stratification and guide treatment in colorectal cancer." (PMID 30646224, 2018). "ZEB2 is a protein that has been identified as important in the metastasis of colorectal cancer." (PMID 29988972, 2018). "This cellular localization was observed in multiple tumor tissue arrays, colorectal cancer, glioma, renal cell carcinoma, suggesting that cytosolic ZEB2 may play additional functions." (PMID 26136338, 2015). "For example, MEF2A promoted tumor proliferation and metastasis by transcriptionally upregulating the expression of ZEB2 and CTNNB1 in colorectal cancer." (PMID 40066751, 2025). "As a canonical EMT driver, ZEB2 also promoted tumor progression and dissemination: its levels tracked with TNM stage in colorectal carcinoma and portended poor prognosis in urogenital cancers." (PMID 40510028, 2025). "GSK3β phosphorylates ZEB2 at Ser705 and Tyr802 in colorectal cancer; this induces EMT, colorectal cancer-cancer stem-like cell properties and metastasis." (PMID 36499447, 2022). "The correlation between the mRNA levels of ZEB2 and TWIST1 was progressively stronger in colorectal cancers with moderate malignancy at G2 level and high malignancy at G3–G4 level, compared to those with low malignancy at G1 level." (PMID 35884488, 2022). "Many studies found miR-377 acts as a tumor suppressor by targeting EGR1, SGK3, XIAP ZEB2 CUL4A and others in lung tumorigenesis, cervical carcinoma, colorectal cancer and ovarian cancer." (PMID 35741709, 2022). "It has been reported that zinc finger E-box-binding homeobox-2 (ZEB2) was overexpressed in most aggressive cancers, such as bladder cancer, gastric cancer, colorectal cancer, and small cell lung cancer and essential for tumor invasion and EMT process." (PMID 32149094, 2020). "H19 acts in colorectal cancer as a microRNA sponge for MiR-138 and MiR-200, which then target zinc finger e-box binding homeobox 1 (ZEB1) and ZEB2 that are important mesenchymal cell markers in EMT." (PMID 33193379, 2020).
colorectal cancer (continued). "In colorectal cancer, the lncRNA H19 was reported to derepress the endogenous genes, Vimentin, ZEB1, and ZEB2, by targeting miR138 and miR200a." (PMID 31752684, 2019). "In our study EMT was detected in samples of colorectal cancer based on coordinated changes in the expression of the following genes: ZEB1, ZEB2, SNAI1, CDH1, and VIM." (PMID 25157365, 2014). "Moreover, miR‐138‐5p plays a tumor‐suppressing function in glioblastoma multiforme and colorectal cancer by inhibiting the expression of NFAT5 and ZEB2, respectively." (PMID 35441482, 2022). "miR-200b, ZEB2, and PTPN13 are downregulated in colorectal carcinoma with serosal invasion." (PMID 36556168, 2022). "We down-regulated the expression of DCBLD2 in colorectal cancer cells, and the mRNA and protein levels of transcription factors upstream of EMT signal, ZEB1, ZEB2 and SNAIL significantly decreased, which suppress epithelial genes and activate a mesenchymal expression program." (PMID 34095137, 2021). "In addition, Prdx2 inhibited EMT in a colorectal cancer model, reducing invasive characteristics, via Twist1, Snail, ZEB1, and ZEB2." (PMID 33182509, 2020). "Furthermore, miR-132 inhibited colorectal cancer invasion and metastasis through targeting ZEB2 (zinc finger E-box binding homeobox 2)." (PMID 26314959, 2015). "This counterintuitive result was well exemplified by the cases of ZEB2 and RAS in the EMT regulatory network, IRS in the signaling network of EGF-EGFR and insulin-IR, MEK and GRB2 in the signaling network of T-LGL leukemia survival, p21 and PDK1 in F2013, and MEK in C2016 colorectal cancer networks." (PMID 31582789, 2019). "A similar targeting profile was observed for hsa-miR-192-5p: the canonical form bound EMT master-regulator ZEB2 and angiogenesis stimulator WNK1, while non-canonical 5′-isomiR regulated two other colorectal cancer oncogenes: NOX4 and MSN." (PMID 36275459, 2022).
Mowat-Wilson syndrome (57 papers, 2007 to 2026). "Mowat-Wilson Syndrome (MWS) is an autosomal dominant genetic disorder caused by heterozygous mutations or deletions in the Zinc finger E-box-binding homeobox 2 (ZEB2) gene." (PMID 41576029, 2026). "Mutations or deletions of Zeb2 cause the neurodevelopmental disorder Mowat-Wilson syndrome, a rare genetic disease characterized by features common to ASD." (PMID 41220606, 2025). "Mowat-Wilson syndrome (MWS) is a rare genetic neurodevelopmental congenital disorder associated with various defects of the zinc finger E-box binding homeobox 2 (ZEB2) gene." (PMID 38474085, 2024). "Mowat-Wilson syndrome (MOWS) is a rare congenital disease caused by haploinsufficiency of ZEB2, encoding a transcription factor required for neurodevelopment." (PMID 38351292, 2024). "The affected boy from the 'c' branch has the autosomal dominant Mowat-Wilson syndrome due to a heterozygous pathogenic variant in ZEB2 (OMIM #235730)." (PMID 37460657, 2023). "ZEB2 deficiency in humans has also been associated with craniofacial abnormalities, such as the excessive growth of the jaw (Mowat-Wilson syndrome)." (PMID 36890579, 2023). "Over 50% of Mowat-Wilson syndrome patients with ZEB2 mutations are reported to have renal and genitourinary abnormalities." (PMID 36445780, 2023). "ZEB2 loss-of-function heterozygous mutations in humans cause Mowat-Wilson syndrome (OMIM #235730), a congenital disorder characterized by intellectual disability, craniofacial abnormalities, and Hirschsprung disease." (PMID 36445780, 2023). "Mowat-Wilson syndrome is usually caused by heterozygous de novo variants in the ZEB2 gene encoding the zink-finger E-box binding homeobox (ZEB) 2 transcription factor." (PMID 36353360, 2022). "For example, Mowat-Wilson syndrome, an autosomal dominant disorder that occurs due to de novo heterozygous mutations in the ZEB2 gene, can involve hypoplasia or agenesis of the corpus callosum and various ocular findings such as strabismus and nystagmus." (PMID 35844343, 2022). "Heterozygous loss-of-function mutations in ZEB2 have been described to cause Mowat-Wilson syndrome, a complex disorder that manifests as an array of brain developmental defects with variable penetrance." (PMID 33765444, 2021). "The pathogenic variants in the ZEB2 (ZFHX1B) gene, intragenic deletions, and microdeletions of the critical region 2q22-23, in which the ZEB2 gene is located, all cause Mowat-Wilson syndrome." (PMID 33982229, 2021). "ZEB2’s previous identification as the causative gene in Mowat-Wilson syndrome further highlights its importance in human neurodevelopment." (PMID 33765444, 2021). "Mowat-Wilson Syndrome (MWS) (OMIM # 235730) is a rare disorder due to ZEB2 gene defects (heterozygous mutation or deletion)." (PMID 34199024, 2021). "ZEB2 has been implicated to be associated with several diseases including Mowat-Wilson syndrome and esophageal cancer." (PMID 33499918, 2021). "Mowat-Wilson syndrome, caused by a 9Mbp deletion in chromosome two including all of ZEB2, was identified in a four-year-old girl (ID 07) with developmental delay, microcephaly, and seizure onset at 28 months." (PMID 34469436, 2021). "Mowat-Wilson syndrome is a rare neurodevelopmental disorder caused by pathogenic variants in the ZEB2 gene, intragenic deletions of the ZEB2 gene, and microdeletions in the critical chromosomal region 2q22-23, where the ZEB2 gene is located." (PMID 33982229, 2021). "Mowat-Wilson Syndrome (MWS) (OMIM # 235730) is a condition due to ZEB2 gene defects (heterozygous mutation or deletion) and is characterized by a wide clinical spectrum that ranges from mild (usually associated with missense mutations) to severe forms." (PMID 34199024, 2021). "Mowat-Wilson syndrome, caused by disease causing variants in the ZEB2 gene on chromosome 2q, is associated with severe learning disability, limited speech, seizures and characteristic facial features that resemble those of AS." (PMID 31235867, 2019).
Mowat-Wilson syndrome (continued). "In humans, mutations on the ZEB2 gene cause Mowat Wilson Syndrome, a disorder associated with mental retardation, microcephaly and short stature." (PMID 27351100, 2016). "In case 3, the diagnosis was Mowat-Wilson Syndrome due to loss of function in ZEB2 gene on chromosome 2q22.3." (PMID 26942024, 2016). "Loss-of-function mutations in ZEB2 cause Mowat-Wilson syndrome, an autosomal dominant disorder characterized by intellectual disability, delayed motor development, and epilepsy." (PMID 26933844, 2016). "Only deletions, inversions, and frameshift mutations in ZEB2 have been reported in individuals with Mowat-Wilson syndrome." (PMID 26933844, 2016). "ZEB2 mutations cause the Mowat-Wilson syndrome, a disease characterized by mental retardation, Hirschsprung disease, microcephaly, and distinct facial malformations." (PMID 25798919, 2015). "As mutations in ZEB2 have been reported in Mowat-Wilson syndrome, a congenital anomaly that presents with CHD, this newly-discovered role of ZEB2 provides novel insights into its role in CHD." (PMID 26485529, 2015). "Based on a comparison with human Mowat-Wilson syndrome, we suggest that deletion of ZEB2, is responsible for most of the effects of the mutation." (PMID 23152852, 2012). "Nervous system disorders and Mowat-Wilson Syndrome are diseases linked to ZEB2." (PMID 39129166, 2025). "It was elucidated in research more than 20 years ago that heterozygous mutation of ZEB2 was one of the etiologic causes of Mowat-Wilson syndrome (MWS), a neurocristopathy characterized by facial gestalt, intellectual disability, microcephaly, congenital heart defects, and Hirschsprung’s disease." (PMID 40510028, 2025). "Human Protein Atlas data showed strong ZEB2 expression in neural and lymphoid tissues; heterozygous loss-of-function variants caused Mowat-Wilson syndrome, manifested by intellectual disability, characteristic facies, epilepsy, and a predisposition to Hirschsprung disease." (PMID 40510028, 2025). "In addition, our study also contributes to explaining developmental disorders, including Mowat-Wilson syndrome caused by ZEB2 deficiency, and also other monogenic syndromes." (PMID 36980900, 2023). "Moreover, to create a mouse model of Mowat-Wilson Syndrome, it is necessary to have a conditional Zeb2 knockout of both alleles, otherwise in the human species an inactivated allele is sufficient to manifest the disease." (PMID 34199024, 2021). "Similarly, several studies have shown that heterozygous mutations of the Zeb2 gene cause the Mowat-Wilson syndrome, which is characterized by seizures with onset in the second year of life, among other symptoms." (PMID 32168507, 2020). "Mutations in ZEB2 are associated with Mowat-Wilson syndrome, a complex developmental disorder." (PMID 24967590, 2014). "Recently, ZEB2 was found to repress Nkx-2.1 expression in the developing mouse cerebral cortex, and loss of this regulation may contribute to Mowat Wilson syndrome." (PMID 25474681, 2014). "ZEB2 is mutated in individuals with Mowat-Wilson syndrome, which has seizures as a common symptom." (PMID 20585627, 2010). "Mowat-Wilson syndrome (MOWS) is a congenital disease caused by de novo heterozygous loss of function mutations or deletions of the ZEB2 gene." (PMID 28422173, 2017). "Mutations in ZEB2 cause Mowat-Wilson Syndrome (MOWS, OMIM#235730), a rare congenital disease." (PMID 36980900, 2023). "Mowat-Wilson syndrome (MWS, OMIM 235730) is a rare autosomal dominant disorder caused by a heterozygous deletion or loss-of-function variant of the ZEB2 gene (zinc finger E-box binding homeobox 2)." (PMID 36406119, 2022). "The role of ZEB2 in nervous system development results in severe neurological involvement in humans with Mowat-Wilson Syndrome due to ZEB2 haploinsufficiency." (PMID 34199024, 2021).